MAPK10 (mitogen-activated protein kinase 10)
Diseases named in the same sentence as MAPK10 in open-access papers (continued):
Sharing a sentence is not in itself a finding about the gene and the disease.
Hepatic steatosis (3 papers, 2013 to 2017). Steatosis is a term used to denote lipid accumulation within hepatocytes. "This final list includes six genes associated with ALT elevation and/or hepatic steatosis (MAPK10, CPN1, TRIB1, PNPLA3, SAMM50 and MICAL3)." (PMID 23813869, 2013). "Microscopic examination of tissue sections demonstrated increased hypertrophy of white and brown adipocytes and increased hepatic steatosis in HFD-fed Mapk10-/- mice compared with HFD-fed WT mice." (PMID 26910012, 2016).
Hyperglycemia (3 papers, 2022 to 2025). An increased concentration of glucose in the blood. "Hyperglycemia induces endoplasmic reticulum stress and increases expression of MAPK10, and 4-phenylbutyric treatment and the knockdown of MAPK10 both alleviate hyperglycaemia-induced myocardial dysfunction, respectively." (PMID 35941186, 2022). "Our findings suggested that MAPK10 is a key molecule in hyperglycemia-induced cardiac remodeling." (PMID 35941186, 2022). "We therefore performed heart-specific knockdown of MAPK10 to verify whether MAPK10 is a key molecule in hyperglycemia-induced cardiac remodeling." (PMID 35941186, 2022). "Therefore, the present study sheds new light on the novel role of MAPK10 in hyperglycemia-induced myocardial dysfunction in db/db mice." (PMID 35941186, 2022). "Thus, MAPK10 is a crucial factor in hyperglycemia-induced DCM." (PMID 35941186, 2022). "Second, we did not conduct an in vitro experiment to validate the hyperglycemia-induced MAPK10 activation." (PMID 35941186, 2022). "The mechanistic findings suggested that hyperglycemia initiated the ERS response through the negative regulation of sirtuin 1 (SIRT1), leading to the occurrence of myocardial dysfunction, and specific knockdown of MAPK10 in the heart directly reversed myocardial dysfunction induced by hyperglycemia." (PMID 35941186, 2022).
schizophrenia (3 papers, 2018 to 2023). A major psychotic disorder characterized by abnormalities in the perception or expression of reality. "Another study conducted on a relatively homogenous population in China found an association between mutations of the MAPK10 gene encoding JNK3 and schizophrenia." (PMID 32998477, 2020).
brain tumors (2 papers, 2014 to 2021). "Somatic mutations were identified in the JNK pathway via large-scale sequencing analyses of human tumor cells, and JNK3 encoding gene (MAPK10) has been speculated to be a putative tumor suppressor gene as almost half of the brain tumors that were examined included mutations." (PMID 24550720, 2014).
colorectal cancer (2 papers, 2012 to 2018). A primary or metastatic malignant neoplasm that affects the colon or rectum. "Briefly, we found that mmu-miR-688 and mmu-miR-30c-1* targeting Tcf712 and Cdk4 are involved in colorectal and pancreatic cancer, respectively, while the same miRNAs targeting Bad, Mapk10, Mapk3 and Tgfbr1 are involved both in pancreatic as well as colorectal cancer." (PMID 22245972, 2012).
head and neck cancer (2 papers, 2021 to 2022). A primary or metastatic malignant neoplasm affecting the head and neck. "MAPK10, also known as JNK3, suppressed the expression of JNK3 and enhanced the toxicity of paclitaxel in head and neck cancer cells." (PMID 34631528, 2021).
hepatic cancer (2 papers, 2021 to 2025). "Collectively, our results showed that differential MAPK10 expression associates with gene expression profiles that are indicative of the distinct cell composition of the liver cancer microenvironment." (PMID 34408980, 2021). "CTSA, CRELD2, MAPK10, and other specific genes are associated with the Ras and MAPK signaling pathways, which have been implicated in tumorigenesis and metastasis of hepatic cancer." (PMID 40901642, 2025). "The expression values of MAPK10 in a form of FPKM in both liver cancer tissues and adjacent normal tissues were transformed onto Log10 scale." (PMID 34408980, 2021). "In summary, our results indicated that MAPK10 abundance has a functional impact on the expression of the cell adhesion and costimulatory molecule ICAM1 in liver cancer cells possibly contributing to the MAPK10 immune effects in the TME." (PMID 34408980, 2021). "As we identified 495 DIGs being correlated with MAPK10 expression in liver cancer patients, we attempted to elucidate the key biological functions of these DIGs in the TME of HCC patients." (PMID 34408980, 2021). "Collectively, these results illustrated that transcriptomically assigned immune activity of liver cancer microenvironment correlates with MAPK10 expression and might potentially be regulated by the MAPK10 kinase." (PMID 34408980, 2021). "Finally, we identified binding cites for the c-jun transcription factor in the promoter of the ICAM1 gene, and we found that the phosphorylation of c-jun at Ser63 is differentially regulated in MAPK10 overexpressing and knock-down liver cancer cells." (PMID 34408980, 2021). "We thus hypothesized that MAPK10 may regulate ICAM1 expression in liver cancer cells by modulating the activity of AP-1TFs." (PMID 34408980, 2021). "Indeed, the statistical analysis showed that the expression of MAPK10 was significantly correlated with the expression of immune genes in the liver cancer microenvironment (Chi-square P < 0.001)." (PMID 34408980, 2021). "We found, by using qPCR, that the expression of ICAM1 in MAPK10-overexpressing HepG2-MAPK10 cell line was significantly higher than in the control HepG2-puro cell line, suggesting that MAPK10 is able to promote the expression of the co-stimulatory molecule ICAM1 in liver cancer cells (P < 0.0001)." (PMID 34408980, 2021). "Additionally, we have preliminary evidence that MAPK10 was frequently down-regulated in liver cancer patients." (PMID 34408980, 2021). "Meanwhile, after the expression values of MAPK10 in HCC patients were transformed onto log10 scale, the mRNA level of MAPK10 in liver cancer tissues decreased in a linear manner." (PMID 34408980, 2021). "Our data demonstrates that MAPK10 expression correlates with ICAM1 expression in the TME of HCC patients, and that MAPK10 is able to functionally influence ICAM1 gene expression in cultured liver cancer cells." (PMID 34408980, 2021).
Senile plaques (2 papers, 2022 to 2023). Senile plaques are extracellular deposits of amyloid in the gray matter of the brain. "Furthermore, patients with AD had significantly increased levels of Mapk10, associated with Aβ in senile plaques." (PMID 35056627, 2022).
small cell lung carcinoma (2 papers, 2020). Small cell lung cancer (SCLC) is a highly aggressive malignant neoplasm, accounting for 10-15% of lung cancer cases, characterized byrapid growth, and early metastasis. "In Cd9KO-network, FAS, of the TNF-receptor superfamily that functions in extrinsic apoptosis pathway, was tagged as a bottleneck-hub, while MAPK10, a pro-apoptotic factor, known to be deleted in small-cell-lung-cancer, was identified as a bottleneck." (PMID 33424923, 2020).
Type 1 diabetes (2 papers, 2020 to 2026). "In addition, MAPK10 is related to fat, liver development, muscle atrophy, type I diabetes, and muscle-invasive tumors." (PMID 32168898, 2020).
acute myeloid leukemia (1 paper, 2022). Acute myeloid leukemia (AML) is a group of neoplasms arising from precursor cells committed to the myeloid cell-line differentiation. "It is worth to mention that a few genes with a role in acute myeloid leukemia: GRB2, CSFIR, MARCKS and PDGFB were upregulated; FLT1, IL6, PIK3C2B, BALAP3 and MAPK10 were downregulated." (PMID 36413544, 2022).
breast tumor (1 paper, 2024). "In contrast, IL18, IL2RG, IL33 and MAPK10 were highly expressed in normal breast tissues, whereas they were expressed at low levels in breast tumor tissues (p < 0.001)." (PMID 38438469, 2024). "The results showed that CCL5 and IDH2 were not significantly differentially methylated in BRCA, while CCR7, EZR, IL8, and IL2RG were hypermethylated in normal tissues, and FLT3, MAPK10, and MMP9 were hypermethylated in breast tumor tissues." (PMID 38438469, 2024).
cyst (1 paper, 2021). A sac-like closed membranous structure that may be empty or contain fluid or amorphous material. "In oomycetes, PsMAPK1, PsSAK1, PsMPK7 and MAPK10 showed various functions in vegetative growth, zoospore viability, stress tolerance, detoxification of reactive oxygen species, cyst germination, sexual reproduction, laccase activity and pathogenicity." (PMID 33805371, 2021).
Down syndrome (1 paper, 2022). "In this group, MAPK10 has recently been shown to be downregulated in patients with Down syndrome and COVID-1946." (PMID 35697915, 2022).
Epileptic encephalopathy (1 paper, 2020). A condition in which epileptiform abnormalities are believed to contribute to the progressive disturbance in cerebral function. "Another case of MAPK10/JNK3 mutation was studied in a patient affected by pharmacoresistant epileptic encephalopathy." (PMID 32998477, 2020).
Intellectual disability (1 paper, 2015). "It should be taken into account that chromosome 4 has been weakly associated with mood disorders, and some genes on chromosome 4, such as RASGEF1B, MAPK10 and JNK3, are associated with intellectual disability." (PMID 26539248, 2015).
laryngeal squamous cell carcinoma (1 paper, 2022). A squamous cell carcinoma that arises from the larynx. "They used a real-time quantitative fluorescence PCR (RT-qPCR) to analyze the mRNA expressions of MAPK10, c-Jun, and Itga6 genes in the pretreatment samples of 57 laryngeal squamous cell carcinoma patients." (PMID 35875133, 2022).
lung adenocarcinoma (1 paper, 2023). A carcinoma that arises from the lung and is characterized by the presence of malignant glandular epithelial cells. "The results showed that the mRNA expression levels of ESR1, DDX3X, MAPK10, KIT, FOXO1, and MCL1 were significantly lower in both lung adenocarcinoma (LUAD) and lung squamous cell carcinoma (LUSC) tissues (p < 0.001) than normal lung tissues." (PMID 38180107, 2023).
lung carcinoma (1 paper, 2025). "Notably, the expression of MAPK10 is associated with the incidence and progression of lung cancer, and heightened MAPK10 expression can enhance the effectiveness of chemotherapy on lung cancer." (PMID 40725119, 2025). "DNAm modifications of MAPK10, PLCG1, PLCβ3 and PIK3R2 genes were consistently linked between the lung and blood samples, suggesting their pivotal role in radon-induced lung cancer." (PMID 40725119, 2025). "miR-21-5p targets the 3′-UTR region of MAPK10, thereby suppressing its expression, implying that MAPK10 may play a tumor suppressor role in lung cancer." (PMID 40725119, 2025). "The DNAm episignatures of MAPK10, PLCG1, PLCβ3 and PIK3R2 have a significant influence on radon-induced lung cancer." (PMID 40725119, 2025). "In addition, radon exposure promoted lung cancer development in the genetic engineering mouse model (GEMM), accompanied by decreased MAPK10 and increased PLCG1, PLCβ3, and PIK3R2 with mRNA and protein levels." (PMID 40725119, 2025). "In this study, radon exposure induced MAPK10 5′-UTR hypermethylation, which was significantly correlated in lung tissues and blood, and its RNA and protein were significantly reduced in lung tissues of KRASG12D lung cancer mice." (PMID 40725119, 2025). "Thus, MAPK10 gene hypermethylation within the 5′-UTR might silence gene expression, and disrupt the equilibrium between cell proliferation and apoptosis, resulting in aberrant signaling pathways, thereby representing a prospective biomarker and prime therapeutic target for radon-induced lung cancer." (PMID 40725119, 2025).
lymph node metastases (1 paper, 2022). "Furthermore, the patients with lymph node metastases (N >0) and high TNM stage (III and IV) showed a lower expression of MAPK10 and an overexpression of Itga6." (PMID 35875133, 2022).
malaria (1 paper, 2015). Malaria is a serious and sometimes fatal disease caused by a parasite that commonly infects a certain type of mosquito which feeds on humans. "The MAPK10 gene is another immune-related gene that is located in an Asian-enriched ancestry segment in the Colombian population, and alleles of this gene were recently shown to be selected for malaria resistance in Malaysia31." (PMID 26197429, 2015). "Adaptive and innate immune system related genes and pathways are particularly over-represented among ancestry-enriched segments, including genes (HLA-B and MAPK10) that are involved in defense against endemic pathogens such as malaria." (PMID 26197429, 2015).
melanoma (1 paper, 2023). A malignant, usually aggressive tumor composed of atypical, neoplastic melanocytes. "The forest plot shows that IFNAR2, LBP, CXCL9, and TLR2 are the protective genes for melanoma, while RAC1 and MAPK10 are the risk genes for melanoma." (PMID 37666853, 2023). "By integrating a series of bioinformatics methods, our study identified 6 TLR-related genes (IFNAR2, RAC1, LBP, TLR2, MAPK10, CXCL9), which have the potential to serve as new indicators of melanoma progression and prognosis." (PMID 37666853, 2023). "Subsequently, employing a similar approach, we conducted a thorough analysis of the correlation between the clinical characteristics of melanoma and remaining five model genes, i.e. IFNAR2, LBP, MAPK10, RAC1, and TLR2." (PMID 37666853, 2023).
osteosarcoma (1 paper, 2023). A usually aggressive malignant bone-forming mesenchymal neoplasm, predominantly affecting adolescents and young adults. "The IHC results illustrated that the expression of AVADVL, ATF4, INS and MAPK10 was higher in osteosarcoma tissues compared to normal tissues." (PMID 37285835, 2023). "In this study, we found significant differences between the prognosis of patients with low and high expression levels of ACADVL, ATF4, HMOX1, INS, and MAPK10, indicating that these genes are potential therapeutic targets of osteosarcoma." (PMID 37285835, 2023). "In the present study, we analyzed the high-throughput RNA-sequencing data and clinical information of 86 osteosarcoma patients, and identified eight prognosis-related genes, including MAP3K5, G6PD, HMOX1, ATF4, ACADVL, MAPK1, MAPK10, and INS." (PMID 37285835, 2023).
Salmonella Infections (1 paper, 2023). Infections with bacteria of the genus SALMONELLA. "Contrary to our expectation, Salmonella infection was also enriched in clusters 1 and 3, and thus, we reviewed the DEGs and found that only six DEGs, such as AHNAK, MAP2K1, MAPK10, ARL8B, IL6, and PFN2, were enriched after S. enterica BNCC186354 infection, but only ARL8B and PFN2 were downregulated." (PMID 36980306, 2023).
vascular dementia (1 paper, 2025). A degenerative vascular disorder affecting the brain. "Both Mapk10 and Gabbr1 are considered potential targets for vascular dementia treatment." (PMID 40699779, 2025).
cancer (37 papers, 2013 to 2025). A tumor composed of atypical neoplastic, often pleomorphic cells that invade other tissues. "While MAPK10 as a gene locus shows variability across cancer types, individual transcripts reveal distinct associations with phenotypic features and patient outcomes." (PMID 41048343, 2025). "High expression of CCR7, IL2RG, CXCL9 and MAPK10 was associated with elevated drug sensitivity of cancer cells, while high expression of FLT3 was associated with diminished drug sensitivity of cancer cells to one drug (INK-128)." (PMID 38438469, 2024). "We found that increased expression of MAPK10 associates with higher transcriptional scores of immune cells and lower scores of cancer cells in the TME of HCC." (PMID 34408980, 2021). "Mapk10 (also known as Jnk3) has been associated with drug resistance and its knockdown sensitizes cells to growth inhibition to at least one anti-cancer drug." (PMID 24658335, 2014). "Notably, distinct MAPK10 transcript isoforms were associated with divergent phenotypes across cancer types." (PMID 41048343, 2025). "MAPK10 (also known as JNK3) has previously been characterized as a tumor suppressor gene across various cancers, playing critical roles in apoptotic signaling and stress response." (PMID 41472741, 2025). "Examples of transcript-specific correlations of MAPK10 with cancer types, phenotypic features, and prognostic outcomes." (PMID 41048343, 2025). "VLCKD-induced nutritional ketosis promoted changes in the methylation of 18 genes (20 CpGs; 17 hypomethylated, 3 hypermethylated) belonged to cancer-related pathways with MAPK10, CCN1, CTNNA2, LAMC3 and GLI2 being the most representative genes." (PMID 40140215, 2025). "These isoform-specific correlations underscore the heterogeneity within the MAPK10 gene locus, where distinct transcripts contribute variably to cancer progression, phenotypic features, and therapeutic responses across cancer types." (PMID 41048343, 2025). "This biomarker works by downregulating mitogen-activated protein kinase 10 (MAPK10), which contributes to the development of cancer." (PMID 40305328, 2025). "The heterogeneity within MAPK10 reinforces the importance of transcriptomics in understanding cancer biology." (PMID 41048343, 2025). "The transcript-level correlations observed for MAPK10 underscore the importance of distinguishing specific isoforms in cancer research and clinical applications." (PMID 41048343, 2025). "High miR-335-5p expression promotes bone formation and regeneration and angiogenesis and regulates cancer progression by targeting MAPK10 or NLRP1/7." (PMID 37082197, 2023). "HCC patients with high expression of MAPK10 had gene expression profiles consistent with lower numbers of cancer cells than those with low MAPK10 expression also per cumulative scoring (Wilcoxon test, P = 1.136 × 10−12)." (PMID 34408980, 2021). "In this study we analyzed expression data from the pan-cancer TCGA database and found reduced expression of the MAPK10 gene in cancer tissue of HCC patients compared to the surrounding normal tissue." (PMID 34408980, 2021). "MAPK10 functions as a tumor suppressor and the deletion of this proapoptotic gene would favor the survival and proliferation of cancer cells." (PMID 32983988, 2020). "Since MAPK10 codes for a protein centrally involved in a host of signalling pathways, it is likely that it is involved in cancer." (PMID 27112211, 2016). "The Nature 2011 dataset yielded staging data correlations with MAPK10 expression where all stages of cancer underexpressed MAPK10 versus normal’s mean of 1.08 ±." (PMID 24423449, 2014). "This approach could be precious in cancers where MAPK10 isoforms contribute differentially to immune infiltrates, such as “cold” or “hot” tumors, potentially guiding the selection of immunotherapy strategies." (PMID 41048343, 2025). "MAPK10 regulates the occurrence and development of several types of cancer." (PMID 33482821, 2021).